CTHRC1 (collagen triple helix repeat containing 1)
Diseases named in the same sentence as CTHRC1 in open-access papers (continued):
Sharing a sentence is not in itself a finding about the gene and the disease.
pancreatic cancer (continued). "As a result, four datasets (GSE62452, GSE183795, GSE15471, and GSE16515) met the inclusion criteria and were used for the comparison of CTHRC1 expression between pancreatic tumor and paired adjacent normal tissue samples." (PMID 37444482, 2023). "Our analyses of the transcriptomes of pancreatic tumor and paired non-tumor tissue samples using publicly available Gene Expression Omnibus (GEO) datasets revealed very similar distribution patterns of CTHRC1 across multiple studies." (PMID 37444482, 2023). "First, the interactions between CTHRC1 and periostin likely occurs exclusively in PSCs, not in pancreatic cancer cells." (PMID 37444482, 2023). "In accordance with the results of our study, the MEK/ERK pathway has been related to CTHRC1 in pancreatic cancer, without identification of any downstream effectors." (PMID 28645305, 2017). "Finally, to further confirm that CTHRC1 in CAFs activates STAT3 signaling in pancreatic cancer cells via LIF regulation, we cocultured CTHRC1‐overexpressing CAFs‐CM with pancreatic cancer cells in the presence of the LIF inhibitor EC330 and STAT3 inhibitor Stattic." (PMID 40751418, 2025). "However, the interactions between CTHRC1 and PSC and the roles of such paracrine actions of CTHRC1 in the remodeling of the pancreatic cancer TME remain unknown." (PMID 37444482, 2023). "Meanwhile, Collagen triple-helix repeat-containing 1 (CTHRC1) secreted by several malignant tumors has been reported to recruit TEMs to the tumor microenvironment through upregulation of Ang-2 in endothelial cells and promote metastasis in human MiaPaCa-2, CFPAC-1, and Panc-1 pancreatic cancers." (PMID 31474975, 2019). "Finally, to further investigate whether CAF‐derived CTHRC1 activates the STAT3 signaling pathway in pancreatic cancer cells via LIF, we cocultured PDAC cells with conditioned medium from CTHRC1‐overexpressing CAFs (CAFs‐CM) in the presence of the STAT3‐specific inhibitor Stattic." (PMID 40751418, 2025). "Moreover, anti-CTHRC1 (up to 20 μg/mL) antibody was not cytotoxic to pancreatic cancer cells." (PMID 37444482, 2023). "Periostin was not secreted by any of the four pancreatic cancer cell lines (MIA PaCa-2, PANC-1, CFPAC-1, and BxPC-3) with or without treatment with CTHRC1 (10, 100, or 1000 ng/mL)." (PMID 37444482, 2023).
melanoma (21 papers, 2012 to 2024). A malignant, usually aggressive tumor composed of atypical, neoplastic melanocytes. "On the other hand, although CTHRC1 was positively correlated with the BRAF(V600E) mutation in melanoma, CTHRC1 expression levels were positively associated with the OS rate in melanoma patients, which was the opposite with colon cancer and thyroid cancer." (PMID 39052013, 2024). "To analyze the diagnostic value of CTHRC1 in colon cancer, thyroid cancer, and melanoma patients, we performed an ROC curve analysis." (PMID 39052013, 2024). "We have previously found that CTHRC1 is an important mediator of melanoma cell migration and invasion in vitro, and that in clinical melanoma tumor samples, CTHRC1 is expressed in melanoma cells, tumor‐associated fibroblasts, and tumor blood vessels." (PMID 32053263, 2020). "Despite the limited sample size, we found a significant association between a shorter survival time and a high CTHRC1 mRNA expression in primary melanomas." (PMID 26918341, 2016). "Since we found that CTHRC1 was further overexpressed in metastatic primary melanomas, we sought to determine if CTHRC1 expression was associated with patient survival." (PMID 26918341, 2016). "As CTHRC1 expression was clearly associated with tumor progression in clinical human melanomas, we unexpectedly found that the growth rate of CTHRC1-knockdown cells was increased compared to the control shRNA cells in two repeated experiments." (PMID 26918341, 2016). "We selected one of these genes, collagen triple helix repeat containing 1 (CTHRC1), for detailed analysis, and found that CTHRC1 was expressed in both melanoma cells and the associated fibroblasts, as well as in the endothelium of tumor blood vessels." (PMID 26918341, 2016). "It is notable that CTHRC1 and many of the genes that we found to be associated with CTHRC1 overexpression during melanoma progression are also induced by TGFβ." (PMID 26918341, 2016). "Consistent with this, we found that the genes correlating with CTHRC1 expression in primary melanoma tissues were most significantly associated with blood vessel development and locomotion." (PMID 26918341, 2016). "To determine if variant 3 accounts for the cellular CTHRC1 protein in melanoma cells, we knocked down the CTHRC1 expression with small interfering RNAs (siRNAs) specific to the full-length or variant 3 mRNA and with siRNAs targeting both splice variants." (PMID 26918341, 2016). "Of particular interest, we found that the collagen triple helix repeat containing 1 (CTHRC1) gene was overexpressed in metastatic primary melanomas, and a high expression of CTHRC1 mRNA was associated with a short survival." (PMID 26918341, 2016). "Next, the association of CTHRC1 expression with clinicopathological parameters in colon cancer, thyroid cancer, and melanoma patients (including age, gender, tumor size, tumor infiltration depth, lymph node metastasis, distant metastasis, and clinical stage) was analyzed based on the TCGA data." (PMID 39052013, 2024). "Therefore, the results of the survival analysis showed that CTHRC1 expression was significantly associated with survival in patients with colon cancer, thyroid cancer, and melanoma." (PMID 39052013, 2024). "Although CTHRC1 expression has been observed in human solid cancers, and aberrant expression of CTHRC1 is associated with cancer tissue invasion and metastasis in melanoma, how CTHRC1 induces these phenotypes has remained unknown." (PMID 24504172, 2014). "Therefore, CTHRC1 could be used as a diagnostic, prognostic, and adjuvant therapeutic biomarker in human colon cancer, thyroid cancer, and melanoma." (PMID 39052013, 2024). "This study provides evidence of a significant correlation between CTHRC1 and the BRAF(V600E) mutation, suggesting its potential utility as a diagnostic and prognostic biomarker in human colon cancer, thyroid cancer, and melanoma." (PMID 39052013, 2024).
melanoma (continued). "In this study, we identified that collagen triple helix repeat containing 1 (CTHRC1) expression was associated with the BRAF(V600E) mutation in colon cancer, thyroid cancer, and melanoma." (PMID 39052013, 2024). "In this study, through database analysis and clinical tissue studies, we demonstrated that the expression of CTHRC1 was significantly associated with the BRAF(V600E) mutation in colon cancer, thyroid cancer, and melanoma." (PMID 39052013, 2024). "In this study, we demonstrated that CTHRC1 was positively correlated with the BRAF(V600E) mutation in human colon cancer, thyroid cancer, and melanoma." (PMID 39052013, 2024). "CTHRC1 and FN are both overexpressed in melanomas where they are found to be localized in similar regions." (PMID 36190948, 2022). "Here, we show that P4HA1 knockdown reduced CTHRC1 secretion in melanoma cells in vitro and CTHRC1 protein deposition around tumor blood vessels in vivo." (PMID 32053263, 2020). "We have previously reported that CTHRC1 is overexpressed in metastatic primary melanomas and plays an important role in melanoma cell migration and invasion." (PMID 32053263, 2020). "CTHRC1 was widely up-regulated in multiple human tumors, such as cancers of the liver, pancreas, and gastrointestinal tract and melanoma." (PMID 33102569, 2020). "It thus appears that the upregulation of CTHRC1 mRNA in the primary melanomas compared to benign nevi primarily results from an increase in blood vessel formation and from the recruitment and activation of stromal fibroblasts." (PMID 26918341, 2016). "Knockdown of CTHRC1 expression by shRNAs in melanoma cells inhibited their migration in Transwell assays and their invasion in three-dimensional collagen and Matrigel matrices." (PMID 26918341, 2016). "Here, we found that one such potential target gene, CTHRC1, was overexpressed by both melanoma cells and the surrounding activated fibroblasts, and showed high expression in tumor blood vessels as well." (PMID 26918341, 2016). "The metastatic MM170 and SKMEL-28, as well as the VGP WM115 and metastatic WM239 melanoma cell lines (the latter two originating from the same patient) showed the highest CTHRC1 mRNA expression." (PMID 26918341, 2016). "The microvascular endothelial cells, in turn, expressed CTHRC1 mRNA at a moderate level similar to the melanoma cells." (PMID 26918341, 2016). "In benign nevi, CTHRC1 showed faint to modest staining, while in primary melanomas and melanoma metastases the CTHRC1 staining varied from moderate to strong." (PMID 26918341, 2016). "In any case, our studies on clinical human melanomas show that CTHRC1 expression in primary melanomas correlates with lymph node metastasis and poor patient prognosis." (PMID 26918341, 2016). "The knockdown of CTHRC1 expression in melanoma cells has been found to decrease melanoma cell migration in vitro, a finding consistent with our results." (PMID 26918341, 2016). "We then tested the effect of endogenous CTHRC1 on cell adhesion by knocking down CTHRC1 expression in WM239 melanoma cells by short hairpin RNAs (shRNAs) targeting all CTHRC1 variants (for the level of knockdown)." (PMID 26918341, 2016). "At the protein level, FN1, ITGB3, and NFATC2 were expressed in a manner similar to CTHRC1 in our panel of melanoma cell lines." (PMID 26918341, 2016). "To confirm the CTHRC1 staining pattern, we additionally stained frozen sections from three primary melanomas with another antibody that recognized the native form of the CTHRC1 protein in Western blotting." (PMID 26918341, 2016). "In melanoma cells, the most intensive CTHRC1 staining was found in areas contacting stromal cells, suggesting that the interplay between melanoma cells and fibroblasts is important in inducing CTHRC1 expression." (PMID 26918341, 2016). "Other genes correlating with CTHRC1 expression in melanoma cell lines included the transcription factor NFATC2 and ITGB3." (PMID 26918341, 2016).
melanoma (continued). "Next, using immunohistochemistry we analyzed the protein expression levels and tissue distribution of CTHRC1 in benign nevi (n = 15), primary melanomas (n = 16), and melanoma lymph node metastases (n = 19)." (PMID 26918341, 2016). "We found that CTHRC1 was expressed by melanoma cells, activated stromal fibroblasts, and blood vessel endothelial cells." (PMID 26918341, 2016). "In our in vivo xenograft experiments in nude mice, we found that knockdown of CTHRC1 in WM239 melanoma cells increased tumor growth." (PMID 26918341, 2016). "To further test the effect of CTHRC1 on melanoma cell migration and invasion in a three-dimensional (3D) environment more closely mimicking the in vivo situation, we plated the cells between two layers of COL-I gel or Matrigel." (PMID 26918341, 2016). "As a result of this and the increased angiogenesis, CTHRC1 is likely to be universally increased in melanomas." (PMID 26918341, 2016). "Among the cancer cells reported to express Cthrc1 are melanomas, hepatocellular carcinoma, oral cancer, breast ductal carcinoma, pancreatic cancer, colorectal cancer, gastric cancer, and dermatofibrosarcoma protuberans." (PMID 24945147, 2014). "They demonstrated that the migratory behaviors of KZ-28 melanoma cells are inhibited by the specific CTHRC1 siRNA oligos." (PMID 25238260, 2014). "Previous studies also found overexpression of CTHRC1 in melanoma and cancers of the gastrointestinal tract, lung, breast, ovary, and many other organs)." (PMID 23922981, 2013). "Our previous studies found that 12 markers including pAkt, Bim, BRG1, BRMS1, CTHRC1, Cul1, ING4, MCL1, NQO1, SKP2, SNF5 and SOX4 were associated with melanoma progression." (PMID 23028750, 2012). "Therefore, while CTHRC1 and the BRAF(V600E) mutation serve as diagnostic and prognostic biomarkers in melanoma, they cannot simply be considered oncogenic biomarkers and exhibit tissue specificity." (PMID 39052013, 2024). "However, systematic prognostic analysis of CTHRC1 and its relation to the BRAF(V600E) mutation in human colon cancer, thyroid cancer, and melanoma still needs further investigation." (PMID 39052013, 2024). "Furthermore, we analyzed the correlation between CTHRC1 expression and immune cell infiltration in colon cancer, thyroid cancer, and melanoma." (PMID 39052013, 2024). "We can conclude that CTHRC1 plays a crucial role in the immune response in colon cancer, thyroid cancer, and melanoma, and CTHRC1 could be used as a potential target for immunotherapy." (PMID 39052013, 2024). "CTHRC1 has been reported to be overexpressed in melanoma cells, leading to melanoma metastasis." (PMID 39052013, 2024). "Therefore, our data suggest that elevated CTHRC1 expression is positively associated with the BRAF(V600E) mutation in colon cancer, thyroid cancer, and melanoma patients." (PMID 39052013, 2024). "However, the OS rates of melanoma patients with high CTHRC1 expression were significantly higher than those of melanoma patients with low CTHRC1 expression (P ═ 0.016)." (PMID 39052013, 2024). "Furthermore, the correlation between CTHRC1 expression and the BRAF(V600E) mutation in colon cancer, thyroid cancer, and melanoma was analyzed." (PMID 39052013, 2024). "CTHRC1 expression was found to be negatively correlated with the overall survival (OS) rate in colon cancer and thyroid cancer patients and positively correlated with the OS rate in melanoma patients." (PMID 39052013, 2024). "As we found P4HA1 knockdown to reduce the secretion of CTHRC1 in melanoma cells in vitro, and our previous results have shown that CTHRC1 is localized in the blood vessels in human melanomas, we further studied the expression of CTHRC1 in the xenograft tumors." (PMID 32053263, 2020).
melanoma (continued). "One of them, prolyl 4‐hydroxylase subunit alpha 1 (P4HA1), proved critical for the invasion and survival of melanoma cells and the deposition of collagens (stained in blue) and CTHRC1 in the extracellular matrix and tumor blood vessel walls, maintaining their integrity." (PMID 32053263, 2020). "CsA treatment was also found to decrease CTHRC1 protein levels in MM170 melanoma cells." (PMID 26918341, 2016). "Again, we found that CTHRC1 localized in both the melanoma cells and stromal fibroblasts." (PMID 26918341, 2016). "Here, we found that cFN co-localized with CTHRC1 in the blood vessels of primary melanoma tumors." (PMID 26918341, 2016). "Furthermore, CTHRC1 was recognized as an important mediator of melanoma cell migration and invasion, providing together with its regulators—NFATC2, TGFβ, and BRAF—attractive therapeutic targets against metastatic melanomas." (PMID 26918341, 2016). "We found that the intensity of CTHRC1 staining in melanoma cells varied in individual melanoma tissue samples, with a stronger staining usually seen at the periphery of the tumor (i.e. in invasion fronts) and in areas where the melanoma cells contacted stromal cells." (PMID 26918341, 2016). "CTHRC1 is overexpressed in many cancers, including gastric, pancreatic, hepatocellular, breast, and non-small cell lung cancer, as well as in melanoma." (PMID 26918341, 2016). "Importantly, we further found that the knockdown of CTHRC1 inhibited the invasive growth of melanoma cells in 3D Matrigel and COL-I gels." (PMID 26918341, 2016). "We also studied which genes are coordinately upregulated with CTHRC1 in primary melanoma tissues." (PMID 26918341, 2016). "In melanoma, CTHRC1 has previously been reported to be expressed by melanoma cells." (PMID 26918341, 2016). "Our functional analyses suggested that CTHRC1 is required for the migration and invasion of melanoma cells in vitro, and that it may participate in regulating the switch between proliferation and invasion in vivo." (PMID 26918341, 2016). "However, we found that CTHRC1 is expressed in in vitro cultured cells and in human melanoma tissue samples by both melanoma and stromal cells." (PMID 26918341, 2016). "Therefore, the CTHRC1/FZDs pathway may play important roles in colon cancer, thyroid cancer, and melanoma." (PMID 39052013, 2024). "Therefore, we provided evidence that CTHRC1 is associated with the BRAF(V600E) mutation and could be used as a diagnostic and prognostic biomarker in human colon cancer, thyroid cancer, and melanoma." (PMID 39052013, 2024). "CTHRC1 expression and the BRAF(V600E) mutation were positively correlated in these three types of tumors, with correlation coefficients of 0.139 in colon cancer (COAD, P < 0.05), 0.794 in thyroid cancer (THCA, P < 0.05), and 0.179 in melanoma (SKCM, P < 0.05), respectively." (PMID 39052013, 2024). "Therefore, the CTHRC1 network may play crucial roles in human colon cancer, thyroid cancer, and melanoma." (PMID 39052013, 2024). "Furthermore, we collected 50 colon cancer tissues, 50 thyroid cancer tissues, and 50 melanoma tissues for clinical analysis from the Department of Pathology, First Affiliated Hospital of Anhui Medical University, and the RNA levels of CTHRC1 were examined by qRT-PCR." (PMID 39052013, 2024). "Collectively, these data suggest that CTHRC1 is associated with poor prognosis in human colon cancer and thyroid cancer, but the association between CTHRC1 and patient prognosis was not significant in human melanoma." (PMID 39052013, 2024). "Thus, elevated levels of FN1 may induce the coordinate expression of CTHRC1 in melanoma cells by activating the αvβ3 integrin receptor." (PMID 26918341, 2016). "Furthermore, the CTHRC1 marker may be a useful marker for primary melanoma and BRMS1 serves an important marker for metastatic melanoma distinguishing form dysplastic nevi." (PMID 23028750, 2012).